IL10 (interleukin 10)
Diseases named in the same sentence as IL10 in open-access papers (continued):
Sharing a sentence is not in itself a finding about the gene and the disease.
COVID-19 (continued). "They found that the sum of TNF-α and IL10 combined could distinguish patients with PIMS apart from the patients with severe COVID-19, as they had higher levels than severe COVID-19 patients." (PMID 33344389, 2020). "Other inflammatory cytokines such as IL-1β, IL-4, IL-2, IL-10, and TNFα have also been found to increase, with IL-6 and TNFα still increased in patients with a neurological symptom profile, and IL-1β was upregulated in patients with persistent COVID-19 symptoms." (PMID 41516418, 2026). "However, elevated plasma levels of TNF-α have been identified in individuals with severe COVID-19 in previous studies, and higher levels of IL-10 have been observed in patients with COVID-19 compared to healthy individuals and also in severe cases of the disease compared to non-severe cases." (PMID 39859379, 2025). "In addition, according to a literature-based pathway, anxiety may upregulate multiple cytokines (IL6, IL10, and TNF) and angiotensin II, which are associated with harmful effects during COVID-19." (PMID 40766923, 2025). "Unlike PTB, extraPTB-COVID-19 is less likely to cause severe pulmonary complications, though it may lead to increased systemic inflammation due to IL-10 and IL-4 upregulation." (PMID 40283612, 2025). "High levels of IL-6 and IL-10, adjusted for age, sex, the presence of comorbidities, and the neutrophil-to-lymphocyte ratio (NLR), showed an elevated risk (OR IL-6 = 4.02; OR IL-10 = 9.36) of presenting pneumonia and COVID-19 compared to pneumonia without COVID-19 in patients." (PMID 40508859, 2025). "Previous studies have already shown that individuals with COVID-19 had high levels of some inflammatory mediators in more severe cases of the disease, such as C-reactive protein, D-dimer, bilirubin, urea, and IL-1β, IL-6, IL-8, IL-10, IL-18, IFN, TNF-α cytokines." (PMID 39861879, 2025). "Interestingly, as observed in human COVID-19 patients with fatal disease (KO and 1A0) and those with severe disease (6A4) had overall, significantly increased systemic levels of G-CSF, IL-6, IL-10, TNF-α, IL-12 (p40), IL-17A, CCL5, and CCL11 compared to those with moderate disease (6A2 and 1A3)." (PMID 40242753, 2025). "Our findings revealed a significant increase in serum IL-10 levels in the immune-enhancing formula group post-intervention, indicating that the formula may affect anti-inflammatory and immune responses in patients with severe COVID-19." (PMID 40002722, 2025). "However, several lines of evidence indicate that a remarkable early increase in IL-10 may have a pathological role in COVID-19 severity." (PMID 40143288, 2025). "Corroborating this suggestion that balanced inflammation may favor the immune response to COVID-19 vaccination, a positive correlation was demonstrated between circulating IgG levels specific for SARS-CoV-2 antigens and IL-10 in both the Allele-2 and Allele-1/2 groups." (PMID 40872872, 2025). "While IL-10 has traditional anti-inflammatory properties, its elevated levels in severe COVID-19 correlate with poor outcomes, probably in response to high inflammation in these patients, and it has been suggested that IL-10 may contribute to T-cell exhaustion." (PMID 41235245, 2025). "Cytokines of particular interest include interleukin-6 (IL-6), tumor necrosis factor-alpha (TNF-α), interleukin-8 (IL-8), and interleukin-10 (IL-10), each having been linked to mortality in conditions such as acute cardiac events, renal failure, sepsis, ARDS, and notably COVID-19." (PMID 40843708, 2025). "However, it has been hypothesized that IL-10 might also play a pathological role in COVID-19 disease progression." (PMID 40143288, 2025). "The systemic inflammatory response observed in acute COVID-19, characterized by elevated levels of cytokines, such as IL-2, IL-10, IL-6, IL-8, C-Reactive Protein (CRP), and Tumor Necrosis Factor (TNF)-alpha, triggers acute phase reactions and, if sustained, may lead to end-organ damage." (PMID 40029921, 2025).
COVID-19 (continued). "Thus, IL-10 is a good predictor of disease progression in COVID-19." (PMID 40160824, 2025). "Moreover, the cytokines TNF, IL5, and IL10 have crucial roles in COVID-19 prognosis." (PMID 40766923, 2025). "In some patients, the level of IL-10 remained elevated at T1 as well as at 31–60 days, suggesting that in these patients the sequelae of COVID-19, especially from the inflammatory point of view, might be prolonged, thereby laying the foundations for the development of long COVID-19 syndrome." (PMID 39194742, 2024). "Furthermore, the five cytokines and chemokines with up-regulated expression during the progression of COVID-19 were interleukin 6 (IL-6), interleukin 10 (IL-10), interferon gamma-induced protein 10 (IP-10), TNF-related apoptosis-inducing ligand (TRAIL), and stem cell growth factor beta (SCGF-β)." (PMID 38710800, 2024). "Elevated levels of TNF-α, CXCL10, CCL2, and IL-10 in COVID-19 patients correlate with reduced populations of specific intestinal bacterial, which suggests that gut dysbiosis may contribute significantly to the development of intense and widespread inflammation." (PMID 38701071, 2024). "Thus, the weakened IFNγ response to SARS-CoV-2 and elevated levels of immunosuppressive IL-10 in both COVID-19 and dengue during the early phase of illness indicates an inadequate antiviral response that could contribute to the severity of the diseases." (PMID 39519178, 2024). "Therefore, it can be inferred that IL-10 can cure COVID-19 ARDS." (PMID 37742314, 2024). "Thus, these interleukin levels cannot be compared to those described by other authors for direct dosing from COVID-19 patients serum (IL-6: 19.55 pg/mL mean; IL-10: 3.66 pg/mL mean; TNF-α: 1.11 pg/mL mean) or vaccinated participants serum (IL-6: 25.94 pg/mL mean; IL-10: 11.08 pg/mL mean)." (PMID 38728294, 2024). "The role of IL-10 and IFNγ might differ during uncontrolled viral replication or severe COVID-19." (PMID 38950078, 2024). "Cytokines such as IL-2, IL-6, TNF-α, IFN-γ, and IL-10 could serve as predictors for early prediction of the severity of COVID-19; hence, this study aimed to evaluate the association of cytokine levels IL-2, IL-6, TNF-α, IFN-γ, and IL-10 with the severity of COVID-19 in Bangladesh." (PMID 38707035, 2024). "Furthermore, MIP-1b is positively correlated with IP-10, IL-10, and G-CSF in COVID-19 patients." (PMID 38793604, 2024). "In addition, findings of increased IL-10 levels in COVID-19 patients presenting with headaches seem to indicate that headaches may be a consequence of high cytokine levels." (PMID 36901059, 2023). "Therefore, the elevated level of serum IL-10 in critical cases of COVID-19 may be related to activated monocytes and macrophages, which are the primary producers of this cytokine." (PMID 37283736, 2023). "Given the critical role played by IL-10 in the promotion of tissue repair and resolution of inflammation it is possible that this cytokine could have a useful impact in recovering physiological homeostasis and ending the post-COVID-19 symptoms." (PMID 37359549, 2023). "Notably, in COVID-19 patients, excessive immune activation and subsequent cytokine storm occur, and to prevent damage to host tissues, immunoregulatory cytokines, such as IL-10, are produced to downregulate the expression of pro-inflammatory cytokines." (PMID 37283924, 2023). "In addition, TGFβ1, TGFβ3, IL-6, and IL-10 may be influential biomarkers of COVID-19 severity during the early phase of infection, whereas Th2 cytokines, IL-4 and IL-13, may be markers of persisting severity." (PMID 37569646, 2023). "Similarly, another study confirmed that several serum pro-inflammatory mediators including IL-2R, IL-6, IL-10, and TNFα are increased in severe (n = 11) compared to moderate (n = 10) COVID-19 patients, while serum IFNγ levels were decreased negatively correlating with disease severity." (PMID 36941580, 2023).
COVID-19 (continued). "Dramatic early proinflammatory IL-10 elevation may play a pathological role in COVID-19 severity." (PMID 37853311, 2023). "Based on this evidence, it has been recently proposed that the sustained increase of IL-10 blood levels might be directly involved in the progression and aggravation of COVID-19 by stimulating release of additional cytokines involved in the “cytokine storm” and/or by accelerating T cell exhaustion." (PMID 37215142, 2023). "Herein, the refractory respiratory failure in patients with COVID-19 was associated with increased CRP, D-dimers, LDH, Ferritin, HMGB1, and IL-33, as well as higher numbers of circulating neutrophils, higher plasma levels of IL-6 and IL-10, and diminished numbers of lymphocytes and platelets." (PMID 37604833, 2023). "Finally, the SARS-CoV-2-related peptides (Pool Spike CoV-2 and/or Pool CoV-2) induced changes in the expression of IL-10 and PD-1 in volunteers who recovered from mild COVID-19, IL-17 in volunteers who recovered from Severe COVID-19, and LAP and co-expression of cytotoxic granules in HC." (PMID 36969257, 2023). "Considering that acute COVID-19 induced higher expression levels of Treg IL-10+ in Mild Recovered volunteers, these results may indicate an improved regulatory activity to aid in an adequate antiviral response leading to the resolution of infection with little tissue injury." (PMID 36969257, 2023). "On the other hand, the increased plasma levels of some pro-inflammatory cytokines such as IP-10, MIP-1α, G-CSF, and IL-10 could suggest a more immunomodulatory effect of MSC rather than immunosuppression in patients with ARDS caused COVID-19." (PMID 36901868, 2023). "Notably, among patients with severe COVID-19, the level was even higher in the blood of patients with auto-Abs to type I IFNs compared to their counterparts (20% increase in the frequency of IL-35+IL-10+ Bregs, P = 0.04)." (PMID 37833265, 2023). "Also, LPS induced higher IL-10 production in post-COVID-19 patients, possible that it may be an attempt to overcome potential IL-10 resistance in this population." (PMID 37753077, 2023). "Indeed, we observed a positive association between 2-AG production and IL-10 and lymphocyte counts and a negative correlation with different COVID-19 markers of hyperinflammation, such as IL-6, sTREM-1 and neutrophil counts." (PMID 36851787, 2023). "Given the pivotal role of IL-10 in immune modulation, this cytokine could have relevant implications in pathologies characterized by hyperinflammatory state, such as cancer, or infectious diseases as in the case of COVID-19 and Post-COVID-19 syndrome." (PMID 37359549, 2023). "Thus, it is more logical to use IL-10 to treat COVID-19 instead of corticosteroid." (PMID 36914565, 2023). "Interestingly, the role of immunosuppressive cytokines, especially IL-10, may also contribute to COVID-19 induced damage to the lungs in later stages of the disease." (PMID 37057213, 2023). "Similarly, mRNA levels of NF-κB target genes, including IL1β and IL10, were significantly increased independently of the severity of COVID-19, and CXCL1 and cyclooxygenase 2 (COX2) mRNA expression was significantly higher in PBMCs from patients with severe and critical COVID-19." (PMID 37310504, 2023). "However, little is known about IL-35 and IL-10 producing Bregs in the context of COVID-19." (PMID 37833265, 2023). "In addition, previous reports revealed that IL-10 and PD-L1 suppress T-cell activity during persistent viral infection, thus giving mechanistic insight towards persistent COVID-19 and the potential role of targeting both cytokines to minimize the long-term sequelae of the disease." (PMID 35529862, 2022). "Interleukin-10 (IL-10) was elevated (median 10.4 pg/ml; percentile range 5.96–30.32; cut-off 5) in 21/22 (95.5%) serum samples (from 12 patients) obtained during hospitalization for COVID-19 in group I. Overall, 11/12 (91.7%) patients showed increased serum levels at least once." (PMID 35057809, 2022).
COVID-19 (continued). "Studies investigating fatal cases of COVID-19 found a profound dysfunction of Tregs in the lungs and pulmonary draining lymph nodes of autopsied patients, as indicated by lower FoxP3 expression, limited IL-10 production, and a paucity of FoxP3+ Tregs compared to surviving and non-COVID-19 controls." (PMID 36582234, 2022). "However, the increase in IL-10 in severe cases of COVID-19 in this investigation could be due to IL-10’s pro-inflammatory activity." (PMID 35958594, 2022). "SOTRs with COVID-19 have higher plasma levels of cytokines such as IFN-λ1, IFN-γ, IL-15, IL-18 IL-1RA, IL-6, MCP-2, and TNF-α as compared to healthy controls, and the levels of GM-CSF, IL-15, IL-6, IL-8, and IL-10 were associated with disease severity in SOTRs." (PMID 35075453, 2022). "A total of 500 COVID-19 patients with elevated cardiac biomarkers were studied for the analysis of myocardial abnormality through cardiac enzymes, inflammatory biomarkers, and the expression analysis of various cytokines, including IL-1, IL-6, IL-10, IL-17, and IL-25 genes." (PMID 36298704, 2022). "Our findings reveal that CRP, SAA, VCAM-1, CXCL10, CCL22 and IL-10 levels are promising biomarkers for COVID-19 disease severity, suggesting that plasma inflammatory mediators could be used as warning indicators of COVID-19 severity, aid in COVID-19 prognosis and treatment." (PMID 35958594, 2022). "Interestingly, the role of immunosuppressive cytokines, especially IL-10 may also contribute to COVID-19 induced damage of the lungs in later stages of the disease." (PMID 35075140, 2022). "A high concentration of IL-10 may be a predictor of a poor prognosis in COVID-19 cases." (PMID 35782361, 2022). "Similarly, IL-6/IL-10 ratios can be used to predict the prognosis of multiorgan dysfunction syndrome and mortality after trauma as well as the severity of disease in both pneumonia and COVID-19." (PMID 35261923, 2022). "Additionally, positive correlations between admission IL-8/CXCL8, MCP-1/CCL2, IL-10, and C-reactive protein plasma levels and Δoxygen supply during hospitalization could predict COVID-19 worsening, and some studies partly corroborate these findings." (PMID 36035415, 2022). "This may indicate that in COVID-19, IL-10 enhances the pro-inflammatory environment." (PMID 35572964, 2022). "Hence, several lines of clinical evidence suggest that such dramatic and early elevation of IL-10 might exacerbate pathogenesis in determining COVID-19 severity." (PMID 35464491, 2022). "However, another hypothesis was made based on recent studies rising IL-10 as a possible proinflammatory cytokine in COVID-19 burden, but this concept must be further tested in detail." (PMID 36248863, 2022). "Furthermore, IL-10 is elevated earlier than IL-6 in COVID-19 patients." (PMID 37521849, 2022). "Recent advances in the pathophysiologic understanding of coronavirus disease 2019 (COVID-19) suggests that cytokine release syndrome (CRS) has an association with the severity of disease, which is characterized by increased tumor necrosis factor α (TNF-α), interleukin (IL)-6, IL-2, IL-7, and IL-10." (PMID 35223745, 2022). "Finally, therapies targeting IL-8/CXCL8- or IL-10 activity may offer therapeutic approaches in COVID-19 treatment." (PMID 36035415, 2022). "However, whether neutrophils can also contribute to augmenting circulating IL-10 levels in COVID-19 has to be explored." (PMID 36139764, 2022). "Similarly, it has been reported that TNF-α, IFN-γ, IL-2, IL-4, IL-6, and IL-10 are also highly expressed in the plasma of COVID-19 patients; moreover, IL-6 and IL-10 are significantly increased in the serum of patients with critical conditions, compared to the moderate ones." (PMID 36422642, 2022).
COVID-19 (continued). "These miRNAs target several pro-inflammatory cytokine and chemokine genes (e.g., TNF, CCL2, CXCL9, CXCL10, IL10, VEGFA) as well as cytokine and chemokine receptors and transduction factors (IL1R1, IL2RA, IFNAR2), reported as upregulated and associated with mortality in COVID-19 patients." (PMID 36032130, 2022). "The presence and ratio of IL-6 and IL-10 may be used as predictors of COVID-19 disease severity." (PMID 35962146, 2022). "Thus, as an anti-inflammatory cytokine, IL-10 may be responsible for the reduced T-cell counts that lead to immunodepression in COVID-19 patients." (PMID 35572964, 2022). "IL-10 produced by Tregs plays an antifibrotic role and significantly contributes to the inhibition on fibroproliferation, suggesting that targeting Tregs could be a potential strategy to treat pulmonary fibrosis in severe COVID-19 patients." (PMID 35874688, 2022). "To better characterize the effect of exogenous IL-10 on the whole-blood cells response after stimulation, we measured 27 different immune factors by Luminex multiplex technology in 26 subjects including 14 COVID-19 patients and 12 NO COVID-19-VCs of study population “B”." (PMID 36148228, 2022). "Taken together, our findings suggest that admission values of lymphocyte counts, neutrophil-to-lymphocyte ratio and the levels of some inflammatory markers (IL8/CXCL8, MCP-1/CCL2, IL-10, and C-reactive protein) may be useful as COVID-19 outcome predictors during hospitalization." (PMID 36035415, 2022). "For instance, while reducing the correlation between DEGs including IL10, CXCL8, NFKB1, ARG1, and SOD2, new strong associations appeared between ELANE, DEFA4, AZU1, CTSG, and LCN2, with an overall tendency to higher relationships amid neutrophil-mediated immunity genes in COVID-19 patients." (PMID 35269470, 2022). "Recent studies noted that severely ill COVID-19 patients show elevated levels of IL-10 which led some investigators to propose that IL-10 might contribute to the severity of the disease, because IL-10 is known to have both pro- and anti-inflammatory properties." (PMID 35039055, 2022). "Previously, the inflammatory biomarkers (IL-6, IL-8, IL-10 and ratio of IL-6 to IL-10), patients’ characteristics (age) and chest CT images (consolidation, emphysema and residual healthy lung parenchyma) have been reported to predict the prognosis of COVID-19 patients." (PMID 34217339, 2021). "However, IL-6 and IL-10 showed a marked increase by COVID-19 severity." (PMID 34460840, 2021). "Given the ability of IL-10 to potently induce T cell activation in various cancer models, a final piece of evidence supporting the potential pro-inflammatory actions of IL-10 in COVID-19, is the observation of overactivated CD8+ T cells despite a reduction in overall CD8+ T cell count." (PMID 34234779, 2021). "Moreover, COVID-19 patients had higher levels of IL-10 (15.2 (12.5) vs. 1.2 (1.4) pg/mL, p = 0.02)." (PMID 33808205, 2021). "Similarly, increases in IL-6, in the absence of increases in IL-10, have been associated with disease progression in a nonhuman primate model of COVID-19." (PMID 34424943, 2021). "Interestingly, the anti-inflammatory marker IL10 was elevated in COVID-19 subjects." (PMID 34838058, 2021). "Moreover the role of microbiota in modulating host immune response, and potentially influencing disease severity also in COVID-19, is confirmed by the inverse correlation of bacterial species depleted in COVID-19 patients, with plasma concentration of several cytokines (IL10, TNF-α, CXCL10, CCL2)." (PMID 34070662, 2021). "Thus, serum level of IL-10 4 to 13 days following COVID-19 might be considered as another prognostic indicator." (PMID 35126355, 2021). "Moreover, antidepressant use has been associated with a reduced risk of intubation or death in hospitalized patients with COVID-19 because the inhibition of ASM decreases pro-inflammatory mediators such as IL-2, IL-6, IL-7, IL-10, TNF-α, C-reactive protein (CRP), and D-dimer." (PMID 34579284, 2021).